CD36 (CD36 molecule (CD36 blood group))
Diseases named in the same sentence as CD36 in open-access papers (continued):
Sharing a sentence is not in itself a finding about the gene and the disease.
infection (continued). "Collectively, these studies identify an essential role for CD36 in the maturation of the PV and Leishmania survival, and demonstrate that alternative models of infection, such as Drosophila, are advantageous for discovery of new host factors involved in the Leishmania-host interaction." (PMID 27280707, 2016). "In vivo infection (cutaneous or systemic) was only performed for CD36." (PMID 24498223, 2014). "In addition, it is notable that CD36 protein clearly appeared on the surface of hepatocytes in both WT and TLR2-deficient mice at 2 d post-infection along with a corresponding increase in gene expression, suggesting that TLR2 is not required for this process." (PMID 24058538, 2013). "Firstly, infections in CD36-deficient mice exhibit no sequestration in lungs and adipose tissue but still develop ECM." (PMID 20941396, 2010). "We examined whether differences in nitric oxide production and/or oxidative burst in response to infection with mycobacteria might account for the restriction of mycobacterial growth in Cd36-/- macrophages." (PMID 20950462, 2010). "However, we observed significantly higher levels of IL-10 by Cd36-/- macrophages over a time course of infection and over a range of multiplicities of infection with both M. marinum and BCG." (PMID 20950462, 2010). "Another highly DEG during infection was CD36 (-1.91-fold change)." (PMID 19925655, 2009). "However, while the replication rate of the parasite was similar in CD36-/- and WT macrophages during the first 48 h of infection, by 72 h parasite proliferation in CD36-/- macrophages was significantly reduced compared to WT suggesting a key role for CD36 in amastigote proliferation." (PMID 27280707, 2016). "Therefore, understanding the role of CD36 in MECs during an infection is important." (PMID 26976286, 2016). "We hypothesized that infection in the oral cavity would have a systemic pro-inflammatory effect, through increasing overall oxidative stress and levels of CD36/SR-B2 ligands (oxLDL/KOdiA-PC), and this would lead to greater CD36/SR-B2-dependent lesion burden." (PMID 25938460, 2015). "In addition, these data suggest that CD36 is necessary for the appropriate cellular compartmentalization and activation of Fyn and that infection–induced ROS may serve as an enhancing factor in the mechanism that results in pulmonary edema." (PMID 23967147, 2013). "To rule out the possibility that the enhanced viral DNA replication in CD36+ EPCs cultured under hypoxia was due to an increase in intracellular virus trafficking after virus had entered the cell, we examined number of viral genomes in the nucleus during early infection." (PMID 21698228, 2011). "Following infection, AIM KO BMDMs demonstrated reduced intracellular lipid droplet formation and lower cell surface expression of CD36 compared to wild-type BMDMs." (PMID 40391046, 2025). "Despite evidence showing widespread host shut-off during infection, we found that HSV-1 infection enhanced CD36 plasma membrane localization, especially in shFASN cells." (PMID 40327680, 2025). "TILT-322 infection of ovarian ascites samples led to downregulation of 14 differentially expressed genes (SLC26A4-AS1, APOE, TREM2, CD36, AC145676.1, VENTX, FP671120.4, AC007663.4, AC112220.2, C1QC, TEPP, AC027796.4, AC016026.1, and C1QA) in ascites samples." (PMID 38910324, 2024). "After infection with S. epidermidis 1457, the proportion of CD163+ macrophages rose to 73 ± 4.2%, while the percentage of CD36+ cells declined to 12.79 ± 2.01%." (PMID 39567551, 2024). "By contrast, the scavenger receptor CD36 shows enhanced binding to PIGJ mutants, potentially explaining a subtle tropism for macrophages detected early in infection." (PMID 39302131, 2024). "Lipid receptor expression, such as CD36 and FABP4, are also increased during macrophage infection by both pathogens, which can explain the augmented intake of free FAs or oxidized-LDL." (PMID 37868347, 2023).
infection (continued). "In each case, blocking CD36-driven FFA uptake and subsequent FAO in hematopoietic progenitors blocked HSPC expansion and emergency hematopoiesis during infection." (PMID 35528134, 2022). "Expression of Lpl, Fn1 and Cd36 were downregulated in both microglia and BMDM from Trem2−/− mice relative to WT mice overtime after infection." (PMID 36333761, 2022). "To understand the impact of CD36 expression on HSC metabolism in response to infection we infected WT CD36+/+ and CD36−/− animals with S. typhimurium 72 hours." (PMID 34880245, 2021). "In context, our present study identifies CD36 upregulation in HSC which mediates fatty-acid uptake and allows HSC expansion facilitating the response to infection." (PMID 34880245, 2021). "However, surfactant lipids have also been reported to upregulate Mtb growth via increased expression of CD36, and the alveolar lining fluid from some patients has also been shown to increase intracellular replication in epithelial cells and exacerbate infection." (PMID 33228849, 2020). "The expression kinetics of UT7/Epo-STI B19V were similar to those for CD36+ EPC, with a maximum reached at 72 h post-infection for both cell lines." (PMID 33353185, 2020). "Bacteria infecting Cd36-/- and Hig2-/- BMDM, which have only partial defects in LD formation, phenocopied infection of wildtype BMDM." (PMID 29370315, 2018). "Infection resulted in significantly diminished uptake of S. pneumoniae by MDM and significantly decreased expression of CD36 at both the cell surface and mRNA level." (PMID 27701435, 2016). "In conclusion, our report demonstrates that similar cell surface innate immune receptors (CD36, SR-A, MARCO and TLR2) play different roles against S. aureus infection, depending on the site of infection." (PMID 24498223, 2014). "Consistent with this is the hepatic overexpression of CD36 in NASH patients and in those with chronic HCV G1 infection." (PMID 24751397, 2014). "In all cases, BCG vaccinated animals had a progressive accumulation of OxLDL, CD36 and LOX1 by day 60 that was significantly increased above values at day 5 of infection." (PMID 22493658, 2012). "Later in infection, particularly after 72 h of co-culture, γδ T cells produced markedly stronger granzyme B, RANTES, IFN-γ, and CD36 transcripts." (PMID 21765931, 2011). "To test this, we experimentally infected Cd36-/- and Cd36+/+ mice with M. bovis BCG and examined the burden of mycobacteria and histopathology over the course of infection." (PMID 20950462, 2010). "Genes involved in fatty acid transport, albumin (ALB), myosin (MYO1B), and the thrombospondin receptor (CD36), were up-regulated during infection." (PMID 19216742, 2009). "CD36, a scavenger receptor localized on the cell surface, participates in several cell functions including lipid metabolism and collaborate with TLR4 in the LPS recognition during early stages of infection." (PMID 40725160, 2025). "In this case, A. lancea and Prabchopoothaweep remedy alone downregulated the production of ICAM-1, VCAM-1, and CD36 on day 13 post-infection, while the expression of ICAM-1, VCAM-1, and CD36 was significantly lower than that in the Art-AL and Art-PT combination treatment groups." (PMID 37730604, 2023). "The expression of Plin2 and Cd36 was also increased by VACV infection, in line with the results of the proteomic analysis, further supporting an increase in lipid uptake and storage during infection." (PMID 36453897, 2022). "Together, these results demonstrate that the expression of PfEMP1, such as VAR2CSA, that does not bind to CD36, is a mechanism by which parasites evade macrophages in order to establish robust infection in vivo." (PMID 35831417, 2022). "In our study, the high expression of CD36 by this subpopulation is in line with the high phagocytic activity in the spleen, although this activity was not sufficient to control the infection in untreated mice." (PMID 36310859, 2022).
infection (continued). "This was consistent with our in vitro infection results of T cells and MDM: Both T cell and MDM produced virus expressed CD36 at similar levels but MDM generated virus could be differentiated from T cell generated virus by the absence of CD26." (PMID 34555123, 2021). "To investigate the role of CD36 on fatty-acid uptake by hematopoietic cells in response to infection we transduced CD36−/− (CD45.2) lineage negative, CD117-positive cells with firefly luciferase (LK+FF)." (PMID 34880245, 2021). "Infection with HIV resulted in a notable increase in surface expression of CD36 and CD32 however there were not consistent changes in the expression of other surface markers across all donors when comparing sham to HIV infected cells." (PMID 31133636, 2019). "Parasite proliferation was detected by 96 h post-infection in both genotypes, indicating that lack of CD36 does not impair L. major proliferation." (PMID 27280707, 2016). "While the CD36-deficient cells also showed a reduced overall level of lysotracker-positive vesicles, and this may contribute to the defect in PV enlargement, these vesicles were still detectable yet did not reduce after infection, as observed in WT macrophages." (PMID 27280707, 2016). "The percentage of infected cells and the average number of parasites per infected cell were similar in WT and CD36-/- macrophages at 4 h post-infection, indicating that CD36 is not essential for parasite phagocytosis." (PMID 27280707, 2016). "Confocal microscopy demonstrated that CD36 was not enriched in the small PVs of L. major at either 6 h or 24 h post-infection." (PMID 27280707, 2016). "The absence of CD36 clustering in L. major tight fitting PVs suggests that the receptor is not involved in this infection." (PMID 27280707, 2016). "At three and five days post-infection, ABPS pretreated mice developed stronger Th1 immune responses against malaria infection with the number of F4/80+CD36+ macrophages and levels of IFN-γ, TNF-α and nitric oxide being significantly higher than in the control group." (PMID 22348301, 2012). "Moreover, infection with the cag PAI mutant H. pylori strain resulted in upregulation of gastric PPAR γ responsive genes (i.e., CD36 and FABP4), suggesting increased PPAR γ activation in vivo." (PMID 23166823, 2012). "These include perilipin 2 (PLIN2), which was increased subsequent to primary infection by E. acervulina and E. maxima, as well as prostaglandin reductase 1 (PTGR1), CD36, and carnitine O-octanoyltransferase (CROT), which were decreased following E. acervulina primary infection." (PMID 22140460, 2011). "This would suggest that CD36 remains the major binding receptor for schizonts and that there is no obvious switch in schizont adherence phenotype during an infection." (PMID 20941396, 2010). "Viability of macrophages, as determined by quantitative MTS assay, was equivalent over 7 days after infection with M. tb between Cd36-/- and Cd36+/+ macrophages (p = 0.578; data not shown)." (PMID 20950462, 2010). "Altogether, the results obtained with SR-BII,SR-BI/CD36 or ΔCterm mutants indicated that while the cytoplasmic tailof SR-BI does not seem to be involved in stimulation of infection by HDL, itcould influence the basal HCV entry efficiency." (PMID 19229312, 2009). "Notably, CD36 expression in cells isolated from the infection site was not only generally higher in CD11c+Ly6Chi monocytes, but also exhibited a substantial increase in infected compared with uninfected CD11c+Ly6Chi monocytes." (PMID 37310793, 2023). "Interestingly, CD36 seems specifically needed for FFA uptake by HSC in response to infection but not in other stress conditions that still rely on FAO." (PMID 35528134, 2022).
infection (continued). "SARS-CoV-2 infection of human primary monocytes up-regulated the pathways involved in lipid uptake such as CD36, the major transcriptional factors involved in lipogenesis, PPARγ and SREBP-1, and the enzyme DGAT-1, which is involved in triacylglycerol synthesis, after 24 hours of infection." (PMID 33326472, 2020). "Moreover, we overexpressed CD36 via lentivirus infection in SGC 7901-NM, a GC cell line with low metastatic potential 24, and evaluated the effect of CD36 on metastatic capability using a three-dimensional (3D) spheroid basal membrane extract (BME) cell invasion assay and a transwell assay." (PMID 31410220, 2019). "Hence, the absence of an upregulation of CD36 following the activation by LPS suggests the lower ability of macrophages to combat infection when they are in a hyperglycemic milieu." (PMID 31415598, 2019). "Interestingly, rapamycin treatment resulted in reduced CD36 protein expression in WAT but not lungs on day 6 post-infection." (PMID 29121917, 2017). "This could explain why in this study infection in the complete cd36−/− mouse KO is no different from that of wild-type mice as the two roles of CD36 could exert a balancing effect." (PMID 28468674, 2017). "Thus, by co-operating with CD14 in both R- and S-LPS loading onto TLR4/MD-2, CD36 can enhance the sensitivity of tissue-resident macrophages in detecting infections by Gram-negative bacteria." (PMID 27073833, 2016). "Notably, unlike amastigotes, promastigote cell contact and internalization did not recruit CD36 within the first 6 h of infection." (PMID 27280707, 2016). "It is possible that the lack of change in vascular permeability observed in the CD36−/− lungs during infection merely reflects a lack of signaling due to the significantly reduced number of iRBCs binding to the pulmonary vascular endothelium in the absence of CD36." (PMID 23967147, 2013). "While CD36 expression inSK-Hep1-CLDN1 cells did not induce infection of HCVcc, the SR-BI/CD36 chimeraand the SES mutant were functional, but, for the latter, infection was reducedin comparison to wt SR-BI, in line with results obtained with HCVpp infection assays." (PMID 19229312, 2009). "Furthermore, we identified that without surface CD36, HSC is not able to switch from glycolytic metabolism towards β-oxidation and does not enter the cell cycle, leading to a higher susceptibility and increased mortality to infection." (PMID 34880245, 2021). "Parasite tissue sequestration and the development of acute stage pathology in P. chabaudi infections of mice lacking CD36 or ICAM-1, their respective wild type controls, and in infections with mutant P. chabaudi parasites lacking the smac gene were compared." (PMID 28468674, 2017). "However, at day 6 post-infection, WT animals had histologic evidence of lung injury characterized by thickened alveolar septae, patchy alveolar edema and increased inflammatory cell infiltration, while the lungs from CD36−/− animals were indistinguishable from the lungs of uninfected controls." (PMID 23967147, 2013). "The mRNA levels of PPAR target genes associated with adipocyte differentiation, including ADRP, FABP4, CD36, APOE, APOC1, ASCL1, were strongly induced in THP-1 cells at 6 or/and 48 h after infection by M. leprae but not stimulation by dead M. leprae, as showed by real-time PCR." (PMID 33075048, 2020). "In order to determine whether adherence to ICAM-1 or to CD36 and the involvement of SMAC was applicable to other rodent malarias, the effect of the lack of these molecules on a P. chabaudi blood-stage infection of C57BL/6 mice was investigated." (PMID 28468674, 2017). "Consistent with the results from microarray experiments, PR/8 infection significantly decreased the mRNA levels of CLEC7A (Dectin 1), macrophage scavenger receptor 1 (MSR1), CD36, and the mannose receptor C type 1 (MRC1) but did not change the expression of MRC2." (PMID 22396727, 2012).
infection (continued). "Together, these data conclude PA is not a TLR ligand, but enters macrophages through CD36, and subsequently mediates metabolism to enhance TLR-dependent cytokine production, which may play a critical role in regulating host response to infection and inflammatory diseases." (PMID 37197687, 2023).
metabolic disorders (83 papers, 2013 to 2026). "CD36, a FA transporter, plays a pivotal role in lipid metabolism and is implicated in various metabolic diseases." (PMID 41267927, 2025). "Currently, the studies have shown that CD36 is an important factor in liver injury associated with metabolic diseases." (PMID 35592528, 2022). "Collectively, these results support future studies to identify potentially cohesive mechanisms underlying lipoprotein lipase- and CD36-mediated nerve injury in metabolic disease, and their potential as therapeutic targets for PN treatment." (PMID 31822493, 2020). "Polymorphism of CD36 gene was more likely to be associated with metabolic disorder such as abnormal FFA, HDL and LDL levels." (PMID 27127449, 2016). "Several studies have shown that CD36 may play an important role in kidney injury associated with metabolic diseases." (PMID 35845925, 2022). "Hence, it is hypothesized that CD36 may be associated with metabolic disorders in the skeletal muscle of obese humans and mice as well as in PA-stimulated C2C12 myotubes." (PMID 36979708, 2023). "We highlight novel insights into CD36 as a therapeutic target, presenting recent advances in targeting strategies for a spectrum of conditions such as inflammatory diseases, infections, metabolic disorders and cardiovascular diseases." (PMID 41676141, 2026). "MiR-20a-5p protects against metabolic disorders by targeting CD36, suggesting its potential as a biomarker for MASLD." (PMID 40668532, 2025). "Apigenin reduces the expression of CD36, a membrane glycoprotein that imports FA into the cells and plays a role in metabolic disorders." (PMID 38629096, 2024). "In recent years, the activation of the PPARγ-CD36 axis has increasingly been suggested as a target for therapeutic intervention in the context of various metabolic disorders." (PMID 38989454, 2024). "As an additional link to circadian rhythm, data from experimental circadian dysregulation studies suggest that circadian rhythmicity and the function of CD36 are closely related and determine the extent of metabolic disease." (PMID 38338958, 2024). "In line with a role of CD36 in lipid metabolism, a recent study showed an expansion of T-bet+ B cells in adipose tissue where they contribute to the metabolic disorder in obese mice." (PMID 37744368, 2023). "A cluster of differentiation 36 (CD36), also known as fatty acid translocase, plays an important role in developing and progressing metabolic diseases." (PMID 40625574, 2023). "CD36 is a clearance receptor that plays a role in the uptake of long-chain fatty acids (FAs) by high-affinity tissues and promotes lipid accumulation and metabolic disorders under excessive fat supply." (PMID 35757483, 2022). "Drugs which enhance BCL6 expression or modify the transcriptional regulation of BCL6 and CD36 represent an effective treatment method for NAFLD and associated metabolic diseases." (PMID 35436984, 2022). "In this review, we look at the molecular links between CD36 and metabolic disease in a broader framework, focusing on pancreatic β-cells and other cell systems during the progression of metabolic disorders." (PMID 34360006, 2021). "As both SGLT2 and CD36 exist in the renal proximal tubules, the crosstalk between these two receptors during metabolic disorders is intriguing." (PMID 34830289, 2021). "Many physiological and pathological factors, such as long-chain fatty acids and proteins containing thrombospondin structural homology domains and oxidized phospholipids, including oxidized LDL (oxLDL), perturb CD36 function and induce metabolic diseases." (PMID 34360006, 2021). "Desulfovibrionaceae has been proved to up-regulate CD36 expression and increase uptake of long-chain fatty acids, leading to metabolic disease." (PMID 33092019, 2020).